GFAP (glial fibrillary acidic protein)
Diseases named in the same sentence as GFAP in open-access papers (continued):
Sharing a sentence is not in itself a finding about the gene and the disease.
glioma (continued). "OPGs are low-grade gliomas with features that include a low proliferation index as well as glial fibrillary acidic protein (GFAP) and oligodendrocyte transcription factor 2 (OLIG2) immunoreactivity, and they are often slow-growing." (PMID 37891793, 2023). "Serum GFAP was significantly increased in Grade 4 glioma and was detected in 63% of all Grade 4 patients compared to 13% of healthy controls, indicating that glioma patients had higher GFAP levels, in accordance with our findings." (PMID 36959545, 2023). "GFAP had the highest discriminatory potential between gliomas and meningiomas, followed by several other candidates." (PMID 36959545, 2023). "GFAP overexpression in GBM is frequently associated with blood–brain barrier disruption, and it is commonly found in patients’ serum as a biomarker for gliomas." (PMID 37886397, 2023). "The glioma components often exhibit the typical characteristics of glioblastoma and have different degrees of anaplasia and glial fibrillary acidic protein (GFAP) expression." (PMID 36756387, 2023). "Co-invasion of human glioma cell lines and astrocytes has been investigated in brain slices labelled with anti-GFAP antibody and imaged after clearing in α-thioglycerol, fructose and RapiClear." (PMID 37261345, 2023). "This difference in expression between the two pathologies is maintained in GFAP protein, which is known to positively correlate with advancing neuroglial tumor grade." (PMID 37377888, 2023). "Glial fibrillary acidic protein (GFAP) is an intermediate filament protein found in gliomas that astrocytes and neural progenitor cells generate." (PMID 37509607, 2023). "Fascin-1 and glial fibrillary acidic protein, GFAP, which is upregulated by sema5A, induce morphological changes in glioma cells and astrocytic differentiation of gliomas." (PMID 37627074, 2023). "Glial fibrillary acidic protein (GFAP) was found positive in 2 of 31 cases (6.5%) and to be important for the differential diagnosis of CM from gliomas and chordomas." (PMID 36438949, 2022). "A separate study will be devoted to deeply investigating the occurrence and distribution of proteins’ citrullination PTM inside pediatric brain tumors, with particular regard to VIM and GFAP peptide fragments and to glial tumors." (PMID 35328618, 2022). "We performed co-staining of the caspase-1 with microglia (Iba1+) and astrocyte (GFAP+), which play important roles in the pathology of gliomas." (PMID 35216164, 2022). "In fact, the increased glial fibrillary acidic protein (GFAP) immunoreactivity, inhibition of replication/differentiation and induction of oxidative stress in C6 glioma cells, and of glial development in vivo, were reported." (PMID 36439198, 2022). "The most common glioma biomarker is the glial fibrillary acidic protein (GFAP), which is expressed by normal glial cells and malignant glial cells." (PMID 35847846, 2022). "Such phenomena correlate with elevated serum levels of GFAP - the main cytoplasmic protein in glioma cells, tumor-related mRNA, tumor microvesicles and exosomes, and whole circulating tumor cells." (PMID 35822134, 2022). "Immunohistochemistry performed on a Ventana Benchmark Ultra System with standard protocols showed that glial tumor cells were positive for GFAP (glial fibrillary acidic protein) with only short processes." (PMID 35018523, 2022). "The intensity of NOX2-positive staining in GFAP-positive glioma cells was significantly elevated in patients with GBM (G4) relative to G1–G3 glioma." (PMID 35158782, 2022). "GFAP (glial fibrillary acidic protein) immunoreactivity was diffusely observed in epithelioid cells and lower-grade glioma cells." (PMID 36505786, 2022). "Vascular mimicry channels lack ECs, and their specific markers are PAS-positive and are formed by glioma cells with a stem-cell-like phenotype characterized by reduced glial fibrillary acidic protein (GFAP) and increased CD133 expression." (PMID 36553127, 2022).
glioma (continued). "The levels of GFAP are reported to be increased in traumatic brain injury, gliomas, aging and neurologic disorders including multiple sclerosis." (PMID 36045388, 2022). "The number of glioma cells that have a subcellular co-localization of NOX2 and GFAP was significantly increased in patients with GBM (G4) relative to that in low-grade glioma (G1, G2)." (PMID 35158782, 2022). "Propofol treatment upregulated the levels of the glioma marker, GFAP, and glioma stem cell markers, Oct4 and Sox2, expressed in PDX tumors." (PMID 35927718, 2022). "Since GFAP is highly expressed in the glioma cells of astrocytomas and glioblastomas, we used GFAP for a marker of glioma cells in glioma tissues from patients with GBM." (PMID 35158782, 2022). "In the present study, TSP2 was derived mainly from the glioma center and was only partially derived from GFAP-positive glial cells." (PMID 36476392, 2022). "Compared with strong expression in gliomas and chordomas, the positivity of GFAP in CM is mainly dura-based and marginal." (PMID 36438949, 2022). "We found that the average mass of GFAP per G144 glioma stem cell was 1.7 × 10−4 ± 0.3 × 10−4 ng and per U251 GBM cell was 3.1 × 10−4 ± 0.8 × 10−4 ng." (PMID 35919979, 2022). "Between June 2011 and March 2018, 260 blood samples from 228 glioma-suspect patients that met the inclusion criteria and test-quality, were evaluated for GFAP+ monocytes (Patient flow chart)." (PMID 33501422, 2021). "These were immunohistochemically double stained with antibodies against the proliferation-associated antigen Ki67 and marker proteins for glioma stem cells (CD133, Nestin, Musashi, CD15, CD44), and differentiated glioma cells (GFAP, MAP2c)." (PMID 34170383, 2021). "In glioma cells, changes in Glial Fibrillary Acidic Protein (GFAP) can affect the invasiveness of glioma cells by affecting the expression of the Dual-Specificity Phosphatase 4 (DUSP4) in focal adhesions." (PMID 33614284, 2021). "We discovered a blood monocyte subpopulation carrying the brain-specific glial fibrillary acidic protein in glioma patients and in patients with brain metastasis and evaluated the diagnostic potential of this finding." (PMID 33501422, 2021). "This EV-mediated interaction between astrocytes and glioma cells was further visualized in vivo in a transgenic mouse model with GFAP-driven tdTomato expression in astrocytes in brains implanted with GFP-expressing glioma cells." (PMID 34298912, 2021). "If this recirculation concept is correct, a potential protein for detection in these recirculated TiMas is a glial fibrillary acidic protein (GFAP), which is primarily expressed in astrocytes and gliomas." (PMID 33501422, 2021). "The abundant expression of GFAP in the cells surrounding the VM channels confirmed the cells as glial tumor cells." (PMID 34287575, 2021). "Regulation of vimentin and GFAP levels by pre-miR-146a are in accordance with a study wherein miR-146a overexpression increased GFAP expression and attenuated proliferation, migration and tumorigenic potential of glioma cells." (PMID 33968923, 2021). "Except Ki67, GFAP and S100, other glioma biomarkers, such as ATRX, IDH1 and 1p/19q statues can also be identified by medical imaging." (PMID 34831392, 2021). "To investigate if untreated microglia-derived sEVs were administered to glioma-bearing mice and also affected astrocytes, we analyzed astrocyte reactivity as GFAP staining by immunofluorescence." (PMID 34440835, 2021). "Noted that all the three glioma cells were GFAP positive, whereas neurons were enriched with PDHE1-A, a metabolic gatekeeper in mitochondrial oxidative phosphorylation." (PMID 33509092, 2021). "In our large series of glioma suspect patients, we found a significant increase in the percentage of GFAP-carrying CD16+ monocytes in all glioma grades and brain metastases." (PMID 33501422, 2021).
glioma (continued). "The resulting gliomas displayed an invasive phenotype and expressed GFAP and S100 markers, which are characteristic of human brain tumors, indicating that this is an effective system to model glioma formation." (PMID 33806933, 2021). "A large-scale evaluation of these cells in 228 glioma-suspect patients demonstrated that for the detection of a cerebral lesion sensitivity of 81% and specificity of 85% can be reached with a CO of 0.6% GFAP+CD16+ monocytes." (PMID 33501422, 2021). "These PGCs were identified through immunofluorescence staining with glial fibrillary acidic protein antibody, an established molecular marker of glioma." (PMID 34454479, 2021). "We found that the glioma tissue was diffusively positive for GFAP, Nestin, slightly positive for Olig2, S-100; the positive rate of Ki-67 was 65% and negative for Vimentin." (PMID 33391433, 2021). "As we had observed dramatic fenestration of endothelium and basement membrane in GBM compared to normal CTX, we were interested in examining its relationship with the external wall of the BBB or BTB by labeling astrocytes or glioma cells with GFAP." (PMID 33579378, 2021). "The HSV-TK/GCV system has been previously used to ablate rat glioma cells (C6 cell line), murine cerebellar neural stem cells (C17.2 cell line), murine GFAP-expressing definitive neural stem cells, and human-ESC-derived, Ki67+ NPCs." (PMID 34938162, 2021). "The majority of the patients (323 of 367, 88%) had GFAP positive (+), and 327 patients with low expression GFAP (90%), combined with four that scored (−), were distributed all over the gliomas grades, including low grade (132, 40%), and high grade (195, 60%)." (PMID 33014836, 2020). "Immunohistochemistry performed on a Ventana Benchmark Ultra System with standard protocols showed that glial tumor cells were positive for GFAP (glial fibrillary acidic protein)." (PMID 32451719, 2020). "It was demonstrated that GFAP levels were significantly higher in glioma patient blood serum when compared with the serum GFAP level in non-glial-origin tumors." (PMID 33227903, 2020). "The model maintained the tumor cells viable and functional, showing over 95% viability after 3 days of culture and expressing GFAP, which is the main marker of glioma cells." (PMID 32365781, 2020). "P2X7R and GM-CSFRα were both expressed individually and co-expressed with GFAP, a marker of glioma cells." (PMID 32908225, 2020). "GFAP is often used to reveal the astrocytic lineage of glial cells and glial tumor cells, and plays a more significant role in tumor pathology, when compared to the differential diagnosis of astrocytoma." (PMID 33014836, 2020). "GFAP is a standard marker of more differentiated astrocytoma (i.e., a type of glioma with astrocyte features)." (PMID 32630739, 2020). "In order to expand predictive effects of radiomics, the investigators aimed to assess the prediction feasibility of glioma grades and the pathologic biomarkers of Ki67, S100, and GFAP in gliomas." (PMID 33014836, 2020). "The machine-learning based radiomics approach was applied to predict glioma grades and the expression levels of pathologic biomarkers Ki67, GFAP, and S100 in low or high." (PMID 33014836, 2020). "Interleukin 6 (IL-6) upregulates the expression of glial fibrillary acidic protein (GFAP) in C6 glioma cells, indicating that it is able to induce the differentiation of these cells." (PMID 33227992, 2020).
glioma (continued). "One prominent feature of the glioma microenvironment is the presence of a large number of reactive astrocytes exhibiting increased GFAP and Cx43 expression in the peri-tumor region." (PMID 32717889, 2020). "More cleaved Caspase-3-positive cells were observed in glioma cells than those in normal astrocytes (GFAP-positive cells)." (PMID 33162824, 2020). "The present result was confusing, that is, the high and low expression levels of GFAP were more correlated to high grade gliomas." (PMID 33014836, 2020). "It has been reported that infiltration of T lymphocytes into the brain of patients with glioma coincides with CCL2 expression in GFAP+ astrocytes." (PMID 32098620, 2020). "RF models performed well for predicting glioma grades and pathologic biomarkers S100, Ki67, and GFAP." (PMID 33014836, 2020). "These spinal tumors expressed classical glioma markers, such as GFAP, Sox2, Olig2, and PDGFRa, and had a lower proliferative index than the corresponding brain tumors." (PMID 32727536, 2020). "A total of 27,000 enriched transcripts were characteristic of glioma, including transcripts encoding epidermal growth factor receptor variant III (EGFRvIII) and glial fibrillary acidic protein (GFAP), within exosomes derived from glioblastoma cells in vitro." (PMID 31979318, 2020). "In the first series of experiments, GB primary cell cultures from patient specimens were characterized to confirm the presence of typical glioma markers, such as GFAP and SOX2." (PMID 31986121, 2020). "These plasmids have been previously used to overexpress the GGGGCC-motif in vitro in U251 glial fibrillary acidic protein–positive glioma cells or in vivo in mouse brain via intraventricular adeno-associated virus (AAV)–mediated delivery." (PMID 33123074, 2020). "Further experiments demonstrated that SATB2 is rarely expressed in glioma cells expressing the differentiation markers (GFAP, TUBB3, and GALC) in human GBMs." (PMID 33124191, 2020). "The tumor cells of xenografts maintained the key immune-phenotype of patient gliomas, as determined by staining using GFAP, vimentin and OLIG2." (PMID 31908598, 2020). "Higher GFAP levels in grade IV glioma compared to all others.Higher level of GFAP expression in the tumor subgroup with high GFAP serum levels." (PMID 30667110, 2019). "A recent meta-study reported about a missing correlation between the amount of GFAP and the grade of gliomas." (PMID 31003495, 2019). "Immunohisto-chemistry revealed that numerous cells expressed GFAP presented as brown granules, suggesting the presence of glioma." (PMID 31737781, 2019). "Single-cell suspensions derived from fresh ex vivo GBM specimens demonstrated that FGL2 expression occurred primarily in the glioma subpopulation that expressed glia-specific marker GFAP (43.3 ± 14.3% of GFAP+ cells)." (PMID 30683885, 2019). "Multiple studies characterized GFAP expression in glioma subtypes leading to the establishment of GFAP as a biomarker for astrocytoma that is still used to date." (PMID 30667110, 2019). "Given the incidence of tumours was higher in Ntv compared with glial-specific GFAP-TVA (Gtv) mice, the authors suggested that the presence of these driving mutations in a neural stem cell lineage is a likely origin for gliomas." (PMID 31505839, 2019). "These cells were identified by immunofluorescence staining with GFAP and Nestin antibody, two known glioma molecular makers." (PMID 30082910, 2019). "The representative stem cell gene, CD133, was only detected in neurosphere glioma cells, and representative differentiated cell gene, GFAP, was downregulated in neurosphere glioma cells." (PMID 31508283, 2019). "The current diagnosis of canine glioma is based on morphologic criteria and immunohistochemistry (IHC), including oligodendrocyte transcription factor 2 (Olig2), glial fibrillary acidic protein (GFAP), and 2′, 3′ cyclic nucleotide phosphatase (CNPase)." (PMID 31803765, 2019).
glioma (continued). "In glioma datasets, GFAP was found to be expressed at mostly medium to high levels, which is also consistent with the literature." (PMID 31500569, 2019). "GFAP positive CD9+ exosomes of total CD9+ exosomes were 7.9 times higher in patients with recurrent glioma (22.8%; 18.2–27.1%) compared to healthy controls (2.9%; 2.7–3.2%) at baseline." (PMID 30667110, 2019). "Previous studies have demonstrated that astrocytes interact with glioma cells triggering an astrocyte phenotypic modification by the upregulation of proteolytic enzymes and strong expression of GFAP, in particular within the tumour." (PMID 31795330, 2019). "We successfully cultured and identified several strains of primary glioma cells, which expressed higher GFAP, the molecular marker of gliomas, and higher GOLPH3 in the perinuclear region." (PMID 31094020, 2019). "In glioma cells, CA increased expression of specific differentiation biomarkers Tuj1 and GFAP inducing differentiation and reducing sphere formation." (PMID 31660066, 2019). "The intensity of GFAP positive signal was stronger in ALTS1C1 astrocytoma tumors than those in GL261 glioma and B16-F0 melanoma tumors." (PMID 31106146, 2019). "An alternative cre line that is commonly used in glioma GEMMs is hGFAP-cre (driven by the human glial fibrillary acidic protein promoter), which is also expressed from pre-natal stages and in the majority of cell types in the brain and spinal cord." (PMID 31505839, 2019). "Quantitative RT-PCR analysis showed decreased expression of Nanog, Sox2, KLF4, nestin and CD133, together with increased expression of the differentiation marker glial fibrillary acidic protein (GFAP) in AP-2α overexpressing glioma cells." (PMID 31534499, 2019). "DbcAMP prompted primary GBM cells to produce more GFAP, indicating a pro‐differentiation effect of cAMP signaling activation in primary cultures from four different clinical glioma tissues." (PMID 31162799, 2019). "In Case 8 with a ganglioglioma component, a more prominent GFAP‐positive glial tumour component was confirmed." (PMID 28833756, 2018). "IFIT5 is expressed in normal glial cells only, and gets upregulated in glioma behaving like a glia cell marker as GFAP." (PMID 29844869, 2018). "Taken together, primary GBM cells in serum-containing medium differentiate, indicated by diminished nestin, increased GFAP intensity, and reduced expression of the putative glioma stem-cell markers, albeit with tumor and culture medium dependent variability." (PMID 29967607, 2018). "Cone signal circuitry (M/L+ cells) and glial tumor microenvironment (GFAP+ cells) were primarily present in organoids." (PMID 30353124, 2018). "In accordance, we found that PAP-1 treatment in glioma-bearing mice significantly decreased peritumoral staining with GFAP, confirming that the increased glutamate transporter activity induced by Kv1.3 inhibition correlates with the reduction of astrogliosis." (PMID 29769580, 2018). "The most prevalent form of glioma is referred to as astrocytoma, based on the predominance of GFAP+ astrocytes-like cells within the tumor mass." (PMID 30583471, 2018). "Anti-GFAP antibodies then allowed immunostaining of human glial tumors and GFAP quantitation using rocket electrophoresis." (PMID 30401897, 2018). "Kv1.3 inhibition also reduces glioma-induced astrogliosis, in accordance with findings in rats with autoimmune optic neuritis, where GFAP expression in the regions of the optical nerve was reduced upon PAP-1 treatment." (PMID 29769580, 2018). "A strong GFAP immunoreactivity is present also in reactive astrocytes within or surrounding non-glial tumours." (PMID 28212850, 2018). "In this study, glial fibrillary acidic protein (GFAP) and proliferation-related protein Ki67 were selected as the classic markers of glioma, and the different fluorescence level specimens were analyzed by immunohistochemical pathology and operation." (PMID 30285781, 2018).